PENK (proenkephalin)
Description:
[Met-enkephalin]: Neuropeptide that competes with and mimic the effects of opiate drugs. They play a role in a number of physiologic functions, including pain perception and responses to stress. [Leu-enkephalin]: Neuropeptide that competes with and mimic the effects of opiate drugs. They play a role in a number of physiologic functions, including pain perception and responses to stress. [Met-enkephalin-Arg-Phe]: Met-enkephalin-Arg-Phe neuropeptide acts as a strong ligand of Mu-type opioid receptor OPRM1. Met-enkephalin-Arg-Phe-binding to OPRM1 in the nucleus accumbens of the brain increases activation of OPRM1, leading to long-term synaptic depression of glutamate release. [PENK(114-133)]: Increases glutamate release in the striatum and decreases GABA concentration in the striatum. [Neuropeptide BAM22]: Neuropeptide that mediates stress-induced opioid analgesia (By similarity). Also possesses non-opioid action by acting as a ligand for MRGPRX1 receptor to induce itch in a histamine-independent manner. [Neuropeptide BAM8-22]: Neuropeptide that induces itch in a histamine-independent manner as well as nociceptive sensations. Acts as a ligand for MRGPRX1 receptor in sensory neurons of dorsal root ganglion: MRGPRX1-binding in the peripheral nervous system elicits itch and scratching, while MRGPRX1-binding in the central nervous system dampens chronic pain. [PENK(237-258)]: Increases glutamate release in the striatum.
Synonyms: PE; PENK-A
Tractability: Antibody: its Gene Ontology location is reachable by antibodies, with high confidence; UniProt places it where antibodies can reach, with medium confidence; UniProt predicts a signal peptide or a membrane-spanning region. PROTAC: ubiquitination databases record sites on it.
Gene: Protein-coding gene on chromosome 8 (56,436,674 to 56,448,048, reverse strand). Ensembl gene ENSG00000181195.
Subcellular location: Cytoplasmic vesicle, secretory vesicle, chromaffin granule lumen; Secreted
Subcellular location (Human Protein Atlas): Vesicles; Predicted to be secreted
Pathways (Reactome):
Metabolism of proteins: Post-translational protein phosphorylation; Regulation of Insulin-like Growth Factor (IGF) transport and uptake by Insulin-like Growth Factor Binding Proteins (IGFBPs)
Signal Transduction: G alpha (i) signalling events; Peptide ligand-binding receptors
Gene Ontology:
Molecular function: receptor ligand activity; neuropeptide hormone activity; opioid peptide activity; opioid receptor binding
Biological process: sensory perception of itch; neuropeptide signaling pathway; sensory perception of pain; signal transduction; behavioral response to ethanol; cellular response to cAMP; cellular response to oxidative stress; cellular response to transforming growth factor beta stimulus; cellular response to virus; cellular response to vitamin D; drinking behavior; G protein-coupled opioid receptor signaling pathway; general adaptation syndrome, behavioral process; glial cell proliferation; locomotory exploration behavior; osteoblast differentiation; positive regulation of behavioral fear response; response to calcium ion; response to epinephrine; response to estradiol; response to ethanol; response to hypoxia; response to immobilization stress; response to lipopolysaccharide; response to nicotine; and 4 more
Cellular component: endoplasmic reticulum lumen; extracellular region; neuronal cell body; neuronal dense core vesicle lumen; axon; axon terminus; cell body fiber; chromaffin granule lumen; dendrite; perikaryon; symmetric synapse; synaptic vesicle lumen
Genetic constraint (gnomAD): Loss-of-function variants: 25 observed, 25.15 expected, observed/expected ratio (o/e) 0.99, 90% interval 0.72 to 1.39. The upper end of that interval is the gene's LOEUF score, 1.39, which puts it in group 5 of 6, group 1 being the genes least tolerant of losing a copy. Missense variants: 353 observed, 353.72 expected, observed/expected ratio (o/e) 1, 90% interval 0.91 to 1.09. Synonymous variants: 135 observed, 138.75 expected, observed/expected ratio (o/e) 0.97, 90% interval 0.85 to 1.12.
Homologues: Orthologues: chimpanzee PENK (99% identical), macaque PENK (97% identical), guinea pig PENK (85% identical), pig PENK (85% identical), dog PENK (84% identical), mouse Penk (83% identical), rat Penk (83% identical), tropical clawed frog penk (59% identical), zebrafish penka (40% identical), zebrafish penkb (34% identical). Paralogues in human: PDYN (26% identical), PNOC (15% identical).
Diseases named in the same sentence as PENK in open-access papers:
PENK is named in the same sentence as 111 diseases in open-access papers, as found by Europe PMC text mining. Sharing a sentence is not in itself a finding about the gene and the disease. The quoted sentences say what the papers report.
acute kidney injury (18 papers, 2021 to 2025). Sudden and sustained deterioration of the kidney function characterized by decreased glomerular filtration rate, increased serum creatinine or oliguria. "Multiple large observational studies have revealed that increases in PENK concentration predict and are associated with the occurrence of acute kidney injury." (PMID 38025210, 2023). "Moreover, elevated PENK concentrations have been linked to both acute kidney injury (AKI) and chronic kidney disease (CKD), as well as long-term kidney outcomes and mortality in various clinical settings, such as heart failure and acute myocardial infarction." (PMID 39135801, 2024). "The first study, which included 101 septic patients, revealed a correlation between PENK levels and the diagnosis and severity of acute kidney injury (AKI) based on the RIFLE criterion." (PMID 38790893, 2024). "Recent evidence suggests an association of plasma Proenkephalin A 119–159 (penKid) with early and successful liberation from continuous renal replacement therapy (CRRT) in critically ill patients with acute kidney injury." (PMID 37430375, 2023). "Recently, proenkephalin (PENK), a monomeric peptide that is freely filtered by the glomerulus and thus reflects glomerular filtration very well, has been shown to be an additional useful predictor of the occurrence of acute kidney injury and heart failure." (PMID 40332103, 2025). "It was observed that patients who developed Acute Kidney Injury (AKI) showed a significant increase in proenkephalin levels in the plasma, reaching 145.0 pmol/l for septic AKI, with a sensitivity of 67.9% and specificity of 98.3%, and an area under the curve (AUC) of 0.796." (PMID 38790893, 2024). "Proenkephalin A 119-159 (penKid) has been suggested as a marker of renal failure and poor outcome." (PMID 34278538, 2021). "Proenkephalin (PENK) has emerged as a pivotal biomarker for the early detection of acute kidney injury (AKI), offering predictive value far earlier than serum creatinine in septic patients." (PMID 39594987, 2024). "Background/Objectives: In the context of acute heart failure, proenkephalin A (penKid) has emerged as a prognostic marker for acute kidney injury (AKI), whereas bioactive adrenomedullin (bio-ADM) has been identified as a significant biomarker linked to shock and organ dysfunction." (PMID 40429608, 2025). "Organ-specific biomarkers, such as the Spns2/S1P axis in lung macrophages, mitochondrial dysfunction in the heart, proenkephalin for early acute kidney injury (AKI), and adrenomedullin for predicting multi-organ failure, offer promising avenues for timely intervention." (PMID 39594987, 2024). "Recently, proenkephalin A (PENK A) has been shown to reflect glomerular dysfunction and to predict new-onset acute kidney injury and heart failure." (PMID 37834463, 2023). "Recently, proenkephalin A 119-159 (penKid) has emerged as a novel biomarker that may more adequately reflect kidney function, particularly in critically ill patients with acute kidney injury (AKI) and under non-steady state conditions." (PMID 40475974, 2025). "AKI, acute kidney injury; AUC, area under the receiver operating curve; CI, confidence interval; sCr, serum creatinine; eGFR, estimated glomerular filtration rate; KDIGO, Kidney Disease: Improving Global Outcomes; PENK, proenkephalin A 119–159; Crea, creatinine." (PMID 40141244, 2025).
diabetes (12 papers, 2011 to 2024). "PENK has also been utilized as a predictive marker in a variety of disorders, including acute myocardial infarction, sepsis, acute ischemic stroke, and diabetes." (PMID 36902318, 2023). "Finally, we investigated whether the expression of the proenkephalin (PENK) messanger RNA (mRNA) encoding the one of the two endogenous ligands of MORthat is, enkephalin, in the duodenum of patients with diabetes." (PMID 33020209, 2021). "The high expression groups of PENK, EFEMP2, UBAP1, MAFF and KLF4 were mainly concentrated on diabetes mellitus (DM)." (PMID 38332532, 2024).
pancreatic cancer (12 papers, 2005 to 2024). "Decreased PENK expression may be due to gene methylation as reported in pancreatic cancer." (PMID 16343351, 2005). "Transfection of miR-148b or miR-152 in pancreatic cancer cells reactivated tumor suppressor genes such as BNIP3, SPARC, PENK, and TFPI-2 by downregulating DNMT1." (PMID 36959680, 2023). "For example, the genes SPARC, UCHL1, NPTX2, PENK, and PDAC were investigated in pancreatic cancer, where they were found to be hypermethylated in patients with pancreatic cancer." (PMID 34771655, 2021). "Furthermore, methylation promoter areas in the cfDNA of pancreatic cancer patients have been found for the genes SPARC (secreted protein acidic and rich in cysteine), UCHL1 (ubiquitin carboxy terminal hydrolase L1), PENK (proenkephalin), and NPTX2 (neuronal pentraxin 2)." (PMID 39200847, 2024).
Sepsis (10 papers, 2022 to 2026). Sepsis is defined as life-threatening organ dysfunction caused by a dysregulated host response to infection. "Likewise, prior studies in septic patients have shown that PENK levels were associated with the severity of sepsis, and were profoundly elevated in the group of patients with septic shock in comparison to patients with sepsis." (PMID 38790966, 2024). "Bio-adrenomedullin (Bio-ADM) and Proenkephalin (PenKid) seem to have a key role in the development of organ dysfunctions induced by sepsis and, therefore, could help in the risk stratification of patients with sepsis at ED admission." (PMID 36556987, 2022). "A critical focus of the review was the incorporation of predictive biomarkers, such as adrenomedullin and proenkephalin, which serve as pivotal elements in the pathophysiological network of sepsis." (PMID 39594987, 2024). "The second study, involving a cohort of 167 patients, found that PENK levels increased with the severity of sepsis and the diagnosis of AKI." (PMID 38790893, 2024). "Plasma proenkephalin-A, urinary dickkopf-2, and urinary C–C motif chemokine ligand 14 have been evaluated in patients with sepsis and septic AKI, in those undergoing cardiac surgery, and in critically ill patients with AKI, respectively." (PMID 38913943, 2024). "In this review, we talk about the main biomarkers that evolve the diagnostic of sepsis and AKI, namely neutrophil gelatinase-associated lipocalin (NGAL), proenkephalin (PENK), and cell-free DNA." (PMID 38790893, 2024). "PENK’s ability to predict severe AKI and KRT underscores its role not just as a renal-specific marker but as a broader indicator of multi-organ dysfunction, a hallmark of severe sepsis." (PMID 39594987, 2024). "Similarly, a study evaluating the role of proenkephalin A in sepsis / septic shock showed that the proenkephalin levels within 24 h of ICU admission were significantly higher in those patients who subsequently developed MAKE or persistent or worsening AKI." (PMID 39279017, 2024). "A possible underlying mechanism observed in an experimental study which, however, warrants extensive testing and further elucidation, is the upregulation of PENK induced by oxidative stress which is known to prevail in septic states and further complicate the multifaceted pathobiology of sepsis." (PMID 38790966, 2024). "In addition, recent studies have shown that PENK levels may predict AKI in patients with sepsis." (PMID 38790966, 2024). "We have selected three promising biomarkers for the diagnosis of AKI and sepsis: NGAL, PENK, and cfDNA." (PMID 38790893, 2024). "Plasma proenkephalin A (PENK) is another functional kidney biomarker of interest with better accuracy to estimate GFR and detect AKI compared to SCr, particularly in critically ill patients with sepsis or septic shock." (PMID 37946280, 2023).
heart failure (9 papers, 2015 to 2025). Inability of the heart to pump blood at an adequate rate to meet tissue metabolic requirements. "Our study identified a connection between plasma proenkephalin levels and numerous outcomes in heart failure patients, including all-cause death, rehospitalization, and decreasing renal function." (PMID 36902318, 2023). "The purpose of this systematic review and meta-analysis is to determine the association between plasma PENK levels and their prognostic values in heart failure patients." (PMID 36902318, 2023). "Proenkephalin (PENK), a stable surrogate, is associated with heart failure (HF) development after myocardial infarction and worse cardiorenal function and prognosis in patients with HF." (PMID 34716603, 2021). "In a previous study in patients with HF, we observed that higher concentrations of PENK were associated with more severe heart failure, worse renal function, and increased mortality." (PMID 34716603, 2021). "We demonstrated that PENK and pro‐SP correlate with heart failure severity reflected by NT‐proBNP levels." (PMID 33742565, 2021). "Two previous studies concluded that proenkephalin A (PENK-A) had predictive capabilities for stroke severity, recurrent myocardial infarction, heart failure and mortality in patients with stroke and myocardial infarction." (PMID 26218633, 2015). "Notably, elevated levels of PENK have been documented in patients with heart failure and are considered a protective mechanism to counter-regulate the sympathetic nervous system overdrive in the early stages of heart failure." (PMID 38057904, 2023). "Second, because this is a meta-analysis of observational research, this study can only show relationships between plasma PENK levels and prognosis in heart failure patients, not a causative relationship." (PMID 36902318, 2023). "Furthermore, the findings of this study may encourage the use of proenkephalin as a predictive marker in patients with heart failure in current clinical practices." (PMID 36902318, 2023). "Furthermore, a novel biomarker known as proenkephalin (PENK) has been studied separately and in combination in the context of heart failure; however, there has been no substantial improvement in cardiovascular mortality." (PMID 36902318, 2023).
prostate carcinoma (8 papers, 2005 to 2022). A carcinoma that arises from epithelial cells of the prostate gland. "Studies have shown that PENK hypermethylation is also associated with other cancers including hepatocellular carcinoma, colorectal cancer, and prostate cancer." (PMID 36403035, 2022). "The hyper-methylation of PENK was also found significantly in prostate cancer, colorectal cancer and lung adenocarcinoma.." (PMID 31641374, 2019). "For example, PENK promoter methylation was demonstrated in prostate cancer, breast cancer brain metastasis, and pulmonary adenocarcinoma, and as a potential methylation biomarker for colorectal, meningioma, and bladder cancer." (PMID 25472429, 2014). "Prostate cancer cells appear to retain their responsiveness to stromal PENK signaling." (PMID 34911496, 2021). "The experiments reported here were designed to show that prostate cancer cells, like normal prostate cells, might also respond to stromal PENK." (PMID 34911496, 2021). "Given the influence of PENK on scTF expression in stem-like LuCaP 145.1, this factor might also be capable of reversing prostate cancer cell reprogramming?" (PMID 34911496, 2021). "Gene expression analysis showed that PENK expression was down-regulated in prostate cancer." (PMID 16343351, 2005). "Therefore, we assessed whether PENK methylation was detectable in urine samples from other urologic cancers (two prostate cancer and six kidney cancer patients)." (PMID 36403035, 2022). "AGR2 is an adenocarcinoma gene upregulated in primary prostate cancer cells, while PENK is a prostate stromal cell-specific gene absent in tumors; both are candidate signaling molecules in prostate stromal/epithelial interaction." (PMID 31146720, 2019). "It is interesting to note that the prostate cancer cell lines, PC3 and C4-2, analyzed expressed STC1 (but not PENK), and it is thus possible that STC1 expression could be contributed by epithelial cells as well." (PMID 16343351, 2005).
bladder cancer (6 papers, 2014 to 2025). "In this study, PENK methylation was identified as a potential molecular biomarker for non-invasive diagnosis of bladder cancer." (PMID 36403035, 2022). "However, the promoter hypermethylation of PENK has been indicated in several malignancies including bladder cancer, colorectal cancer and pancreatic cells." (PMID 32195260, 2020). "In urine samples, the methylation status of a urinary biomarker panel (HOXA9, ONECUT2, PCDH17, PENK, TWIST1, VIM, and ZNF154) showed great prediction accuracy in predicting bladder cancer in patients with hematuria." (PMID 37627900, 2023). "A 5-gene panel was identified (NKX6-2, CA10, DBC1, MYO3A, and PENK or SOX11) and the panel had an 85% sensitivity and a 95% specificity for the detection of bladder cancer." (PMID 37627900, 2023). "Eight genes (NKX6-2, A2BP1, CA10, DBC1, MYO3A, NPTX2, PENK, and SOX11) were significantly highly methylated in the urine sediments of bladder cancer patients as compared to that of control subjects." (PMID 37627900, 2023). "Here, we established a combination methylation assay of HOXA9, ONECUT2, PCDH17, PENK, TWIST1, VIM and ZNF154, which had displayed great prediction accuracy of bladder cancer in patients with hematuria by using urine samples." (PMID 31777606, 2019). "In conclusions, a urinary combined methylation assay of HOXA9, ONECUT2, PCDH17, PENK, TWIST1, VIM and ZNF154 displayed accurate prediction of bladder cancer in hematuria patients, which provided the guidance for the patients at early stage tumor and during the follow-up after operation." (PMID 31777606, 2019).
chronic kidney disease (6 papers, 2019 to 2025). Impairment of the renal function secondary to chronic kidney damage persisting for three or more months. "Finally, we discussed the role of PENK in perioperative and intensive care setting, as an emerging biomarker, as well as in chronic kidney disease." (PMID 40332103, 2025). "Proenkephalin A 119–159 (penKid) is a reliable surrogate marker for the more unstable endogenous opioid peptide enkephalin, which has previously been shown to predict both acute and chronic kidney disease." (PMID 31779591, 2019).
breast carcinoma (5 papers, 2014 to 2022). "We have previously reported the association of PENK hypermethylation in breast cancer metastasis to the brain." (PMID 26380585, 2015). "Then, we identified SLIT3, FBLN-1, and PENK as active protein ligands secreted from CD36+ FBs that induced growth suppression of MDA-MB-231 breast cancer cells and determined their minimum effective concentrations." (PMID 36361532, 2022). "Overall, CCL19, CCL21, GPR183, P2RY13, and PENK were potential protective factors in breast cancer." (PMID 32195260, 2020).
acute myocardial infarction (4 papers, 2015 to 2023). Necrosis of the myocardium, as a result of interruption of the blood supply to the area. "Our findings are in contrast with a previous study showing that after myocardial infarction, higher concentrations of PENK were independently associated with a higher risk of developing HF." (PMID 34716603, 2021).